TAAR1 (trace amine associated receptor 1)
Diseases named in the same sentence as TAAR1 in open-access papers (continued):
Sharing a sentence is not in itself a finding about the gene and the disease.
psychosis (21 papers, 2016 to 2025). "Despite TAAR1 being an attention‐grabbing receptor associated with psychosis recently, little has been reported on the molecular pharmacological properties of its ligands." (PMID 38317588, 2024). "TAAR1 agonists appeared to be associated with more dropouts due to any reason compared to placebo in participants with psychosis over treatment of 4–6 weeks." (PMID 39036710, 2024). "Therefore, we co-produced a living systematic review and meta-analysis of human and non-human studies to examine the efficacy, tolerability, and underlying mechanism of action of TAAR1 agonism for psychosis." (PMID 39036710, 2024). "Given the putative role of TAAR1, subjects carrying such sub-functional receptors might be predisposed to several mental disorders, including psychosis, mood disorders, attention-deficit/hyperactivity disorder (ADHD), and addiction." (PMID 29375386, 2017). "Several lines of evidence have implicated TAAR1 in the etiology of psychosis." (PMID 27092049, 2016). "Therefore, we will conduct a living systematic review and meta-analysis to synthesize and triangulate the evidence from preclinical animal experiments and clinical studies on the efficacy, safety, and underlying mechanism of action of TAAR1 agonism for psychosis." (PMID 38634067, 2023). "Although most clinical progress has focused on psychotic disorders, accumulating preclinical evidence indicates that TAAR1 activation also influences anxiety- and stress-related phenotypes." (PMID 41462983, 2025). "For the first time, we combined a quantitative synthesis of data from human and non-human sources of evidence regarding the efficacy, tolerability, and mechanism of action of TAAR1 agonists in treating psychosis, which goes beyond previous reviews." (PMID 39036710, 2024). "With the ongoing development of new TAAR1 agonists, more evidence is needed to understand their potential role in the treatment of psychosis." (PMID 39036710, 2024). "What are the effects of TAAR1 agonists on neurobiological measures relevant to psychosis such asdopaminergic, glutamatergic and serotonergic signalling in preclinical animal experiments of psychosis?" (PMID 38634067, 2023). "What are the effects of TAAR1 agonists on neurobiological measures relevant to psychosis such asdopaminergic, glutamatergic and serotonergic signalling in individuals with psychosis?" (PMID 38634067, 2023). "What are the effects of TAAR1 agonists onbehavioural measures relevant to psychosis in preclinical animal experiments of psychosis?" (PMID 38634067, 2023). "Together, these data persuasively implicate TAAR1 in the etiology and neuropathology of psychosis, and support the investigation of TAAR1-based pharmacological tools as treatments for this condition." (PMID 27092049, 2016). "We aimed to understand if TAAR1 agonists can reduce symptoms of psychosis, what adverse events they might have, and how they work." (PMID 39036710, 2024). "Thus, the TAAR1 mechanism of action still holds promise for the treatment of psychosis, with emerging evidence expected in the near future." (PMID 39036710, 2024). "Additionally, the findings from animal models of psychosis indicated that TAAR1 agonists potentially exert their beneficial effects through TAAR1-dependent inference with dopaminergic signalling." (PMID 39036710, 2024). "Trace amine-associated receptor 1 (TAAR1) agonism shows promise for treating psychosis, prompting us to synthesise data from human and non-human studies." (PMID 39036710, 2024). "What are the effects of TAAR1 agonists on thesymptoms of psychosis in individuals with psychosis?" (PMID 38634067, 2023). "What are the reportedside-effects of TAAR1 agonists in preclinical animal experiments of psychosis?" (PMID 38634067, 2023). "What are thetolerability and side-effects of TAAR1 agonists in individuals with psychosis?" (PMID 38634067, 2023).
psychosis (continued). "Although additional studies are necessary to further elucidate the potential interaction between TAAR1 and 5-HT1A in vitro and in vivo, compounds with dual TAAR1/5-HT1A activity may provide additional benefits in the treatment of psychosis, mood and anxiety." (PMID 34947997, 2021). "Our study demonstrates for the first time to our knowledge that an experimental model induces the same dopaminergic phenotype seen in patients with psychosis, and the potential of targeting PV interneurons and a novel TAAR1/5HT1A agonist to reverse the dopaminergic phenotype." (PMID 32382134, 2021). "Notwithstanding this, the preclinical evidence to date suggests that TAAR1 agonism may represent a unique approach to modulate the presynaptic DA dysfunction observed in psychosis." (PMID 34947997, 2021). "In vivo, the use of TAAR1 agonists lowered hyperlocomotion in pharmacologic, i.e., cocaine-induced, and genetic, i.e., DAT-knockout (KO), models of hyperdopaminergia, allegedly a hallmark of psychosis." (PMID 29375386, 2017). "For instance, the formation of heterodimers between TAAR1 and the dopamine receptor 2 (D2R) has been observed and allegedly leads to recruitment of β-arrestin 2 and silencing of the GSK3β, a pathway known to be involved in psychosis and mood disorders and targeted by lithium treatment." (PMID 31572197, 2019). "TAAR1 agonists did not appear to have an effect compared to control on locomotor activity in animals subjected to both models of psychosis and TAAR1 knockout (N=2, SMD= -0.02, 95%CI: -1.15, 1.12)." (PMID 39036710, 2024). "Given the evidence that abnormal dopaminergic function is implicated in psychosis, the relationship between D2, TAAR1 and LSD’s psychotic-like effects deserves further consideration in terms of both the neurobiology and the neuropsychopharmacology of psychosis." (PMID 27886063, 2016). "Ulotaront, a TAAR1 agonist with 5-HT1A agonist activity, is a useful compound in patients with psychosis also due to its lack of extrapyramidal symptoms or metabolic side effects." (PMID 40430486, 2025). "There is an unmet need for new therapeutic agents to treat psychosis, especially agents that can lower presynaptic DSC without the side effects seen with current antipsychotics and TAAR1 agonists could play a role in that toolbox." (PMID 40098750, 2024).
Obesity (15 papers, 2016 to 2025). Accumulation of substantial excess body fat. "Beyond its physiological role, TAAR1 has been implicated in pathological processes underlying metabolic disorders, including obesity and metabolic syndrome." (PMID 41155326, 2025). "Genetic evidence shows that naturally occurring TAAR1 variants have been identified in individuals with obesity and impaired glucose homeostasis." (PMID 41155326, 2025). "In summary, we identified TAAR1 variants in a patient cohort affected by overweight/obesity and disturbed glucose homeostasis." (PMID 29225575, 2017). "The purpose of this study was the identification and characterization of potential TAAR1 variants in patients with overweight/obesity and disturbed glucose homeostasis." (PMID 29225575, 2017). "Phentermine, which has been prescribed as an appetite suppressant to control obesity and acts as an agonist to the human TAAR1 (Trace Amine Associate Receptor 1), displayed an MIC of 375.00 μM and was not tested further due to the high concentrations required for inhibitory activity." (PMID 30861059, 2019). "Thus, TAAR1 agonism may be a novel therapeutic strategy for treating T2D and also shows potential for the pharmacotherapy of obesity from both drug- and diet-induced causes." (PMID 34943862, 2021). "Further, the recent demonstration of the ability of TAAR1 agonists to prevent binge eating allows such compounds to address both the centrally mediated over-consumption and subsequent insulin resistance and hormone imbalance aspects of obesity and associated metabolic disorders." (PMID 34943862, 2021). "The described genetic and preclinical findings are of significant relevance for potential TAAR1 agonist therapeutics since obesity, hyperglycemia, insulin resistance and dyslipidemia constitute major side effects of current antipsychotic drug (APD) classes." (PMID 38237896, 2024). "Here, we use a combination of approaches to evaluate the effects of three TAAR1 agonists on metabolic parameters in rodent models of diabetes, obesity, and iatrogenic weight gain." (PMID 38237896, 2024). "Intriguingly, recent preclinical evidence has also identified TAAR1 as a novel regulator of metabolic control and a potential target for obesity and type 2 diabetes." (PMID 38237896, 2024). "Activation of TAAR1 has beneficial effects on glucose control and body weight in animal models of type 2 diabetes and obesity by incretin-like effects." (PMID 37624466, 2023). "TAAR1 agonist decreased food intake and body weight in a diet-induced model of obesity with improved insulin sensitivity and plasma triglyceride levels." (PMID 34943862, 2021). "A considerable body of preclinical evidence supports TAAR1 as a promising target for the treatment of metabolic syndrome and obesity, substance abuse, sleep disorders characterized by changes in REM sleep, and potentially mood and anxiety disorders." (PMID 34947997, 2021). "In particular, TAAR1 activation has been reported to reduce fasting glucose levels, delay gastric emptying, enhance satiety, and suppress food intake, effects that highlight its therapeutic relevance for obesity management." (PMID 41155326, 2025). "TAAR1 agonists have emerged as promising therapeutic agents capable of modulating glucose homeostasis, enhancing insulin secretion and suppressing appetite, making them attractive candidates for the treatment of obesity and related metabolic disorders." (PMID 41155326, 2025). "A significant role of TAAR1 and probably other TAARs in type 2 diabetes and obesity was indicated." (PMID 35625001, 2022). "Furthermore, 3-iodothyronamine (T1AM), an agonist of another member of the TAAR family, TAAR1, has been investigated as a potential anti-obesity drug affecting fatty acid catabolism and pyruvate toward gluconeogenesis in the liver and adipose tissue." (PMID 33799339, 2021). "TAAR1 also regulates nutrient-induced hormone secretion and may be a therapeutic target for diabetes and obesity." (PMID 34946184, 2021).
Obesity (continued). "Interestingly, these dysfunctions may be mitigated by TAAR1 ligands, as activation of TAAR1 by agonists has been shown to improve glycemic control and promote body weight in rodent models of obesity and diabetes." (PMID 41155326, 2025). "Computer simulations have also shown other potential mechanisms of action, of which TAAR1 and serotonin 5-HT2C receptors are particularly interesting for the treatment of obesity and metabolic syndrome." (PMID 37624466, 2023). "Therefore TAAR1 with an incretin-like mechanism could be a new target for treating T2D and obesity." (PMID 34943862, 2021). "Since TAAR1 releases the hormones peptide tyrosine-tyrosine (PYY) and glucono-like peptide 1 (GLP-1), TAAR1 antagonists may regulate obesity." (PMID 34946184, 2021). "In summary, we show that TAAR1 agonists as a class, including the clinical drug-candidate ulotaront, not only lack APD-induced metabolic liabilities but can reduce body weight and improve glycemic control in rodent models of diabetes, obesity, and/or iatrogenic weight gain." (PMID 38237896, 2024).
Parkinson disease (15 papers, 2016 to 2024). A progressive degenerative disorder of the central nervous system characterized by loss of dopamine producing neurons in the substantia nigra and the presence of Lewy bodies in the substantia nigra and locus coeruleus. "Our analysis of the dataset by (GDS4135) revealed that TAAR1 RNA expression is positively correlated with increasing Braak staging, a clinical measurement of the progression of Alzheimer's and Parkinson's disease." (PMID 29997511, 2018). "In disease states of hypo-dopaminergic dysregulation such as Parkinson’s disease, a recent study has shown that TAAR1 signaling is also involved and that TAAR1 antagonism could potentially slow the progression of the disease." (PMID 30233365, 2018). "The limitation of our study is, however, the lack of direct evidence for the role of TAAR1 in the neurobiology of Parkinson’s disease." (PMID 37686140, 2023). "However, the selective TAAR1 agonist RO5166017 has been reported to impact pre- (glutamate release) and post-synaptic (phosphorylation of AMPA receptors) glutamatergic neurotransmission in the striatum of a Parkinson’s disease mouse model." (PMID 38110609, 2024).
Anxiety (11 papers, 2017 to 2025). Intense feelings of nervousness, tension, or panic often arise in response to interpersonal stresses. "Recent studies indicate that TAAR1 agonists can attenuate anxiety-like behaviors in experimental models of PTSD; however, the molecular mechanisms underlying this effect remain poorly understood." (PMID 41462983, 2025). "Its exclusion limits the anatomical scope of the findings and leaves open questions regarding region-specific TAAR1-dependent mechanisms within canonical stress–anxiety networks." (PMID 41462983, 2025). "Research has examined the potential anxiolytic effects of selective TAAR1 agonists on various anxiety-like behaviors." (PMID 40351432, 2025). "Several preclinical studies have investigated the role of TAAR1 in PFC functioning as well as the effect of TAAR1 modulation on cognition, mood- and anxiety-related behaviors." (PMID 34947997, 2021). "TAAR1 knock out mice show a worse performance in anxiety and working memory tests, and they are more prone to develop ethanol addiction." (PMID 29375386, 2017). "The average distance covered by the TAAR1-KO mice in the open arms of the maze in the EPM test was significantly higher than those in the WTd control group, which may indicate a decrease in anxiety in mice with the TAAR1 gene knockout." (PMID 36976665, 2023). "The consumption of a high-fructose diet may be due to the influence on the metabolism processes by dopamine in the brain, neuromotor function, and level of anxiety of TAAR1 knockout mice." (PMID 36976665, 2023). "Thus far, only a few studies have investigated the role of TAAR1 in social, anxiety and depression-related behavior." (PMID 34947997, 2021). "While reduced caudal self-grooming may support an anxiety-like profile already reported in TAAR1-KO mice, the parallel inhibition of rostral grooming suggests a rather global reduction of this behavior, perhaps paralleling concomitant increase in the locomotor activity." (PMID 36430544, 2022). "In addition, TAAR1 activation in mice attenuates stress-induced hyperthermia and improves chronic stress-induced social avoidance, suggesting potential antidepressant and/or anti-anxiety effects." (PMID 34947997, 2021). "Notably, preclinical studies have highlighted the potential of ulotaront (SEP-363856), a TAAR1 agonist currently in II/III clinical trials to treat schizoprenia, MDD, and anxiety." (PMID 40351432, 2025). "In addition to TAAR1, the emerging role of the TAAR5 receptor in anxiety-like behaviors is an intriguing area of research." (PMID 40351432, 2025). "The average distance covered by the TAAR1-KO mice in the open arms of the maze in the EPM test was significantly higher than the WT control group, which may indicate a decrease in the anxiety of the TAAR1-KO mice." (PMID 36976665, 2023). "The average distance covered by the mice in the TAAR1-KO group in the open arms of the maze in the EPM test was significantly higher than the WT control group, which may indicate a decrease in the level of anxiety in the mice with knockout of the TAAR1 gene." (PMID 36976665, 2023).
breast carcinoma (10 papers, 2018 to 2023). "On the other hand, in breast cancer, Vattai and colleagues reported that TAAR1 expression correlates with the tumor differentiation grade, so an overexpression of TAAR1 was associated with a significantly longer survival." (PMID 33113952, 2020). "Cadaverine exerted its effects through the trace amine-associated receptor-1, 2, 3, 5, 8, 9 (TAAR1, 2, 3, 5, 8, 9), of which TAAR1 was already associated with the inhibition of breast cancer growth." (PMID 30934972, 2019). "Previously, TAAR1 was also found to be related to inhibition of breast cancer growth and with a favorable effect on the overall survival of patients with primary breast cancer." (PMID 35783895, 2022). "TAAR1 is widely expressed including placenta, brain, spinal cord, immune cells such as leukocytes, macrophages and dendritic cells, breast cancer tissue, D-cells in stomach, and pancreatic β cells." (PMID 34445181, 2021). "In T1AM stimulated breast cancer cells, additional co-stimulation with estradiol leads to an upregulation of TAAR1 expression." (PMID 34445181, 2021). "Our previously published study showed that an increased TAAR1 expression is correlated significantly with a positive survival rate in breast cancer patients." (PMID 34445181, 2021). "In a previous study, we investigated that TAAR1 overexpression (IRS ≥ 6) is a positive prognostic marker for the OS in early breast cancer." (PMID 33334070, 2020). "Furthermore, low grading (G1) in breast cancer tissue similarly correlates with high TAAR1 expression." (PMID 34445181, 2021). "In recently published studies, investigations were made on the degradation products of thyroid hormones can bind to the trace amine-associated receptor 1 (TAAR1), which is a G-protein coupled receptor that influences the viability and migration of breast cancer cells." (PMID 33334070, 2020). "Since TAAR1 is able to modulate the activity of monoamine receptors that are involved in the regulation of BC growth, TAAR1 and potentially other TAARs may be regarded as prospective therapeutic targets for breast cancer." (PMID 37759760, 2023). "In previously published studies, we could show that TAAR1 expression is a positive prognostic factor for OS in breast cancer patients and that stimulation of breast cancer cell lines with T1AM leads to an increase in TAAR1 expression and a decrease in cell viability." (PMID 34445181, 2021). "Cadaverine binding to TAAR1, TAAR8, and TAAR9 modulates neoplastic properties of breast cancer cells, and TAAR1 expression is enabled in response to the growing concentration of its ligand T1AM in vitro." (PMID 35053262, 2022). "With regards to TAAR1, nuclear sub-cellular distribution has previously been seen in some, but not all, breast cancer cell lines, although the functional relevance of this has yet to be determined." (PMID 34769007, 2021). "Indeed, higher expression of TAAR1, TAAR2, TAAR4, TAAR5, TAAR8 (in ER- cases) and TAAR9 provided better survival in breast cancer." (PMID 30718646, 2019). "Breast cancer studies (n = 12) yielded an average HR of 1.05 which would suggest no differential effect of TAAR1 on cancer survival." (PMID 29997511, 2018).
diabetes (8 papers, 2017 to 2025). "Genotype frequencies of the TAAR1 variants p.Arg23Cys and p.Ser49Leu of diabetes-free individuals from the population-based SHIP-cohort." (PMID 29225575, 2017). "Additionally, for DRD2 functionally connected with TAAR1, the mean semantic similarity values were slightly but significantly lower in the diabetes mellitus samples compared to healthy subjects’ mucosa." (PMID 39062162, 2024). "Meanwhile, we discovered specific changes in co-expression patterns that may suggest the involvement of TAAR1 and D5 receptors in pathologic or compensatory processes in FD or diabetes accordingly." (PMID 39062162, 2024).